INS (insulin)
Diseases named in the same sentence as INS in open-access papers (continued):
Sharing a sentence is not in itself a finding about the gene and the disease.
diabetes (continued). "Diabetes mellitus (DM) is a chronic and heterogeneous metabolic disorder characterized by the presence of hyperglycemia due to deterioration of insulin secretion, defective insulin action, or both." (PMID 38875549, 2023). "Type 2 diabetes mellitus (T2DM) and sarcopenic obesity (SO) are also closely related, as resistance to insulin leads to impaired uptake and use of cellular glucose, leading to numerous consequences such as obesity." (PMID 36672642, 2023). "He had been using an Ayurvedic medication, Insulin Management Expert (IME-9), for his type 2 diabetes mellitus and was found to have severe lactic acidosis that was resistant to initial fluid resuscitation and Ayurvedic medicine-induced liver injury." (PMID 36909122, 2023). "Overall, ROS modulation of insulin signaling and growth pathways such as the AKT/PI3K and mTOR pathways contribute to the progression of diabetes and the development of diabetic vascular complications." (PMID 36670985, 2023). "Another type of diabetes is type 1 diabetes (T1DM), where one’s autoimmune system attacks its own β-cells in the pancreas, which secretes insulin; thus, patients need to depend on insulin injections for blood glucose control." (PMID 37259043, 2023). "Moreover, the findings of the currently available clinical studies have demonstrated that LCDs and intermittent fasting in obese patients (containing those with simultaneous insulin independent diabetes) may result in body fatty mass decline and improvements in metabolic parameters." (PMID 38201865, 2023). "12.1% of patients had diabetes before TPIAT, and 78%, 73%, and 71% were insulin-dependent at 1, 2, and 3 years after TPIAT, respectively." (PMID 37727384, 2023). "Amidst the subset of DEGs, the prominent gene signatures include INS, INSR, DNAJC3, OMA1, GOS2, and CALR which have been reported to be differentially expressed in type 2 diabetes mellitus and/ or metabolic disorders." (PMID 37943808, 2023). "Furthermore, latest advances in 3D printing technology and microfluidic systems could contribute to the rapid development of a simultaneous continuous glucose and insulin monitoring for improving diabetes management towards personalised medicine by providing tailored optimal insulin dosages." (PMID 37504117, 2023). "Thus, a comprehensive interpretation of both studies supports that the residual risk of thromboembolic events among AF patients with diabetes requiring insulin therapy is not insignificant in a real-world setting, even in the background of chronic OAC and regardless of the OAC type (VKAs or NOACs)." (PMID 35976428, 2023). "The “Diabetes Prevention Trial-Type 1” (DPT-1) clinical trial evaluated the effects of subcutaneous and oral insulin administration in patients with stage 2 T1D." (PMID 37297566, 2023). "In the second half of the 1970s, it was definitively recognized that there are two different types of diabetes with different pathophysiologies: T1DM, otherwise referred to as insulin-dependent DM, and T2DM, also called insulin-independent DM." (PMID 37893225, 2023). "Other glycemic variables, such as fasting glucose, post-load glucose, fasting insulin, post-load insulin, and HOMA-IR, were also higher in the incident diabetes group." (PMID 37109236, 2023). "Compared with participants without endpoints, participants with an endpoint event had higher BMI and greater proportions of diabetes, previous MI, previous PCI, multi-vessel CAD, and use of insulin and oral hypoglycemic drugs (all P < 0.05)." (PMID 36864455, 2023). "Diabetes mellitus was observed in a CRC patient treated with pembrolizumab and insulin therapy and management of electrolytes were provided." (PMID 37188271, 2023). "However, how to prevent and manage hypoglycemia in IBD patients, especially in those without diabetes, maybe a major challenge associated with the clinical use of in insulin." (PMID 37491256, 2023).
diabetes (continued). "The International Society of Pediatric and Adolescent Diabetes (ISPAD) recommends metformin (MET) use for metabolic disturbances and hyperglycemia, either in combination with insulin therapy or alone." (PMID 36835611, 2023). "Metabolic diseases, including diabetes mellitus (DM), metabolic syndrome (MS), fatty liver (FL), atherosclerosis (AS), and obesity, are characterized by dyslipidemia, insulin resistance, defective insulin secretion, glucose intolerance, and chronic inflammation." (PMID 37111299, 2023). "Metformin, commonly used in diabetes treatment, is also an activator of AMPK, which inhibits gluconeogenesis in the liver, promotes fatty acid oxidation and improves insulin sensitivity, thereby lowering blood glucose levels." (PMID 37538846, 2023). "For example, high-fat diet (HFD)-fed mice are a commonly used model to mimic human diabetes as HFD mice are hyperglycemic, exhibit increased hepatic glucose production, and are insulin resistant." (PMID 37233701, 2023). "Research into the safety and efficacy of combining SGLT2 inhibitors with other diabetes medications, such as GLP-1 receptor agonists, insulin, and traditional oral agents, can provide insights into optimal combination strategies." (PMID 37908957, 2023). "Cell therapy, in which the expression of insulin or GLP-1 is accurately controlled in vivo, provides a novel strategy for diabetes treatment." (PMID 37384125, 2023). "For instance, hydrogel nanomaterials employed in continuous subcutaneous insulin infusion (CSII) have shown improvements in blood glucose control and reduced therapeutic time in pediatric patients with type 1 diabetes mellitus." (PMID 37504412, 2023). "Analysis of pancreatic islets with CGRP-specific monoclonal antibodies in mouse models of diabetes and diet-induced obesity showed that CGRP blocked glucose-stimulated insulin secretion and reduced the expression of the insulin-2 gene." (PMID 36678160, 2023). "Age (p=0.002), duration of diabetes (p=0.005), body mass (p=0.03), HDL among men (p=0.001), SGOT (p=0.03), insulin (p<0.001), HOMA-IR (p<0.001), and QUICKI (p<0.001) were significantly different between dietary GI tertiles." (PMID 37674617, 2023). "Future research can address interventions designed to provide guidance for insulin dosing based on the CGM data as well as ways for caregivers and others receiving remote CGM data to support their loved ones with diabetes self-management." (PMID 40303270, 2023). "Patients with comorbid type 2 diabetes mellitus (T2DM) and renal disease, particularly those treated with insulin, often require complex pharmacological treatment and management of other diabetes complications." (PMID 37152098, 2023). "Individuals with type 2 diabetes mellitus (T2DM) exhibit hyperglycemia as the result of increased hepatic glucose production, peripheral insulin resistance, relative insulin insufficiency and β-cell dysfunction, ultimately leading to β-cell failure." (PMID 36769296, 2023). "Type 2 diabetes mellitus (T2DM) is a metabolic disease characterized by increased blood glucose levels resulting from disturbances of insulin secretion, insulin action, or both." (PMID 36694216, 2023). "Insulin therapy is the mainstay of treatment for type 1 (T1DM) and type 2 (T2DM) diabetes mellitus patients." (PMID 37240580, 2023). "We also matched the items and number of oral antidiabetic drugs, insulin use, and DCSI scores to balance the severity of diabetes and increase the comparability between the study and comparison groups." (PMID 36876083, 2023). "The etiology behind DE/ED in type 1 diabetes is unknown however contributing factors may be insulin-dependent weight (re)gain after diagnosis, incessant glucose monitoring and subsequent insulin dosage, adding dietary restraint and preoccupation as part of the diabetes management." (PMID 36754894, 2023).
diabetes (continued). "DPP‐4, the enzyme that converts PYY1‐36 to PYY3‐36, is thought to be a mediator of the link between obesity and diabetes by inactivating incretins such as GLP‐1, and regulating inflammation and insulin resistance in the liver and adipose tissue." (PMID 36345253, 2023). "Type 2 diabetes mellitus (T2DM) is a multifactorial disease characterized mainly by decreased insulin sensitivity, impaired insulin secretion, and chronic inflammation." (PMID 36836906, 2023). "For example, rats induced with diabetes present with increased PDK activity in skeletal muscle as well as lower glucose oxidation, and insulin reverses these effects." (PMID 37941908, 2023). "Among the various types of diabetes, type 1 DM (T1DM) is characterized by the destruction of insulin-secreting pancreatic β cells." (PMID 38666044, 2023). "Type 2 diabetes mellitus (T2DM) is characterized by elevated blood glucose levels and insulin resistance (accompanied by increased insulin secretion at the onset of the disease) and has severe effects on the entire body." (PMID 37626968, 2023). "Type 2 Diabetes mellitus (T2DM) is a metabolic disorder mainly characterized by chronic hyperglycemia, insulin resistance, and insufficient insulin secretion." (PMID 37305094, 2023). "Advanced age, known previous diagnosis of diabetes, low HbA1c values, previous comorbidities (high CCI), insulin treatment during their stay, and previous outpatient insulin treatment were associated with both mild and severe hypoglycemia." (PMID 38044455, 2023). "Even though this study brings important information about insulin injection practice and HRQOL among adult diabetes patients, it has some limitations." (PMID 37143082, 2023). "In people with diabetes, SGLT2 inhibitor-induced glycosuria modestly increases blood ketone levels by increasing the glucagon:insulin ratio." (PMID 37159343, 2023). "Type 1 diabetes mellitus (T1DM) is an autoimmune-driven condition characterized by the targeted depletion of pancreatic β-cells, which are responsible for insulin production." (PMID 38313841, 2023). "Despite the availability of effective insulin treatments, long-term consequences, such as diabetic retinopathy (DR), are common in both T1DM and type 2 diabetes mellitus (T2DM)." (PMID 35669071, 2022). "PI3K/AKT signaling is a major pathway in insulin, and aberrant PI3K/AKT signaling is a common pathogenesis of diabetes." (PMID 36467890, 2022). "Diabetes develops in IUGR rats with a phenotype similar to type 2 diabetes in humans, namely progressive dysfunction in insulin secretion and action." (PMID 36714657, 2022). "Diabetes mellitus (DM) is a group of chronic metabolic conditions, all of which are characterized by elevated blood glucose levels resulting from the body’s inability to produce insulin or resistance to insulin action or both." (PMID 35061820, 2022). "Type 2 diabetes mellitus (T2DM) is a complex and heterogeneous disease that primarily results from impaired insulin secretion or insulin resistance (IR)." (PMID 36497154, 2022). "At the same time, our experimental results showed that HLBW lowered glucose levels and increased insulin sensitivity compared with those in the model group, which suggested that HLBW has potential therapeutic value for diabetes." (PMID 35707467, 2022). "In a mouse model of diabetes, it has been demonstrated that KEAP1 knockout, by promoting NRF2 activation, improved insulin secretion and insulin resistance and resulted in the prevention of hyperglycemia." (PMID 35955599, 2022). "Advancements in diabetes technology such as continuous glucose monitoring (CGM), insulin pumps, and automated insulin delivery provide opportunities to improve glycemic control for youth with type 1 diabetes (T1D)." (PMID 35273814, 2022). "In a diabetes animal model, SIRT1 was expressed in pancreatic β-cells and increased insulin secretion in response to glucose." (PMID 35469171, 2022).
diabetes (continued). "CS therapy partially alleviated diabetes in a multiple low-dose STZ-induced diabetic mouse model, which is similar to the later stage of type 2 diabetes with a mild impairment of insulin secretion." (PMID 35308228, 2022). "The Diabetes Control and Complications trial (DCCT) demonstrated that intensive insulin therapy in persons with type 1 diabetes leads to a lower incidence of distal symmetrical polyneuropathy." (PMID 35298717, 2022). "Nonetheless, it is interesting to note that non-insulin glucose-lowering drugs, not only DPP4 inhibitors and SGLT2 inhibitors but also GLP1 analogues, are starting to be used in hospital diabetes management." (PMID 35315989, 2022). "Preparations of insulin (intradermal, intranasal, and oral) have not been able to prevent diabetes onset in those at risk and those having islet autoantibodies; however, higher doses of oral insulin may have effects in those genetically at risk for T1D prior to the development of autoantibodies." (PMID 35328581, 2022). "One of the most prevalent metabolic illnesses, Type 2 Diabetes Mellitus (T2DM), is brought on by a confluence of two mainfactors: improper insulin secretion by pancreatic beta-cells and improper insulin response in insulin-sensitive organs." (PMID 37701509, 2022). "The GLP-1 and insulin secretion rhythm are consistent in both physiological and pathological states, and multiple factors might explain the pathological mechanisms of insulin resistance and diabetes from another perspective by altering the GLP-1 secretion rhythm by L cells." (PMID 36531506, 2022). "Insulin therapy is indicated for survival in T1DM and some cases of specific type of diabetes (e.g., pancreatectomy for pancreatic tumors) and for better glycemic control in T2DM, GDM and other forms of specific type of diabetes." (PMID 36672580, 2022). "Positive control analysis on type 2 diabetes mellitus (T2DM), insulin secretion, insulin resistance, and obesity-related traits was conducted to validate the selection of instrumental variables." (PMID 35654594, 2022). "Compared to other types of diabetes, microvascular complications are less frequent and less severe in patients with CFRD, probably because of the minimal amount of endogenous insulin secretion in these patients." (PMID 35887806, 2022). "In the early stage of diabetes (≤5 years), patients with SIRD, MARD, and MOD can meet their hypoglycemic needs with non-insulin drugs." (PMID 36457559, 2022). "After successful modeling, the mice were divided into four groups: the control group (CON), the diabetes mellitus group (DM), the dapagliflozin treatment group (DM + DAPA), and the insulin treatment group (DM + INS)." (PMID 35281932, 2022). "Because DKA and HHS are more likely to occur when patients do not use sufficient glucose-lowering medications, specifically insulin, this association suggests cost-related rationing, nonadherence, or inability to obtain the medications that patients need to adequately manage their diabetes." (PMID 35040969, 2022). "Patients with diabetes mellitus type 1 (DM1) have lost their ability to produce and secrete insulin due to the selective destruction of beta cells in the pancreatic islets of Langerhans." (PMID 36213069, 2022). "Though adequate insulin production still needs to be optimized and glucose regulated insulin secretion would be ideal, these experiments demonstrate that SC retain their protective properties through genetic modification and might represent a viable option for treating diabetes." (PMID 36555540, 2022). "In adults, diabetes mellitus (DM) manifests as hyperglycemia induced by β cells in the pancreas (type 1 diabetes) or impaired insulin sensitivity (type 2 diabetes), wherein there is a defect in insulin secretion, insulin action, or both." (PMID 36289921, 2022). "In diabetes patients, BER has been reported to promote insulin sensitivity and boost lipid and glucose metabolism by activating adenosine monophosphate-activated protein kinase." (PMID 35975320, 2022).
diabetes (continued). "Concordant with the diabetes subgroups in ANDIS, among the two predominant subgroups, Indian individuals in the SIDD subgroup had the lowest insulin secretion (HOMA2-B) and the highest blood glucose levels while those in the MOD subgroup had the highest BMI." (PMID 34689214, 2022). "No notable difference was found between the two groups in general data including age, gender, diabetes duration, BMI, HBA 1c, and fasting insulin (all P > 0.05)." (PMID 35392498, 2022). "Diabetes mellitus (DM) is a metabolic syndrome highlighted mainly by both chronic hyperglycemia and abnormalities in fat and protein metabolism due to either the inadequate secretion or impaired action of insulin." (PMID 35453376, 2022). "Hence, introducing exercise programs in Diabetes could be considered as a potential tool for its benefits on patients’ health such as improvements in glucose metabolism and insulin sensitivity, though this should be confirmed by studies that allow cause-effect relationships to be established." (PMID 36554003, 2022). "Complex chemical compounds act on multiple diabetes targets in three main regulations of T2DM (regulation of glucose and lipid and insulin secretion/sensitivity)." (PMID 35807241, 2022). "Here, we present data to show that HDAC6 levels are regulated by the lncRNA H19 in the skeletal muscle during diabetes and this regulation modulates IRS1 levels, thereby exerting effects on insulin signaling." (PMID 35842608, 2022). "The dependency of IgG strength on acute and recurring infections, the last of which would raise insulin autoantibodies (IAA) and islet cell autoantibodies (ICA), supported the view of increased continuing autoimmune and overt diabetes after viral infections." (PMID 35733062, 2022). "Insulin is one of the main treatments for ICU clinicians to treat hyperglycemia of critically ill patients, which is partly similar to the treatment of diabetes." (PMID 35968315, 2022). "The molecular basis of HNF1A abnormality in insulin secretion in human beta cells and the pathophysiological role of HNF1A in the liver, kidneys, and gut in diabetes requires further investigation." (PMID 35328643, 2022). "Altogether our results suggest that vitamin B6 treatment is effective in rescuing diabetes induced by PI3K depletion, possibly by enhancing insulin sensitivity." (PMID 35678366, 2022). "In chronic hyperglycaemia, present in diabetics, an increase in IAPP:insulin ratio is usually observed." (PMID 35475576, 2022). "Consequently, insulin is one of the most widely used hypoglycemic agents in all forms of DM, with the benefit of improving glycemic control in addition to lowering rates of diabetes-related complications." (PMID 35227220, 2022). "Diabetes mellitus (DM) occurs when insulin-secreting pancreatic β- cells malfunction." (PMID 36144741, 2022). "The dysfunction and/or reduced mass of pancreatic β-cells results in impaired glucose-stimulated insulin secretion (GSIS), leading to diabetes." (PMID 35562869, 2022). "MicroRNA 29a has been reported to be one of the strongest candidate Mirna regulatory hubs in the T2DM gene network, as well as one of the most upregulated miRNAs in various insulin-sensitive tissues in T2DM patients and rodent models of diabetes." (PMID 36160451, 2022). "These targets are enriched in multiple pathways related to type 2 diabetes mellitus, including adipocytokine, AMPK, TNF, HIF-1, PI3K-AKT, NOD and TOLL-like receptors, mTOR, glucagon, and insulin signaling pathways." (PMID 36160451, 2022). "Highlights Our study suggests that people with diabetes (PWD) face issues of affording and obtaining insulin and diabetes supplies, even in a population predominantly on private health insurance." (PMID 36562281, 2022). "Type 2 diabetes mellitus (T2DM) is a persistent state of hyperglycemia and glucose intolerance that occurs when the body cannot respond fully to insulin, followed by an increase in insulin production and a subsequent insulin deficiency." (PMID 35568946, 2022).